NEDD4L (NEDD4 like E3 ubiquitin protein ligase)
Description:
E3 ubiquitin-protein ligase that mediates the polyubiquitination of lysine and cysteine residues on target proteins and is thereby implicated in the regulation of various signaling pathways including autophagy, innate immunity or DNA repair. Inhibits TGF-beta signaling by triggering SMAD2 and TGFBR1 ubiquitination and proteasome-dependent degradation. Downregulates autophagy and cell growth by ubiquitinating and reducing cellular ULK1 or ASCT2 levels. Promotes ubiquitination and internalization of various plasma membrane channels such as ENaC, SCN2A/Nav1.2, SCN3A/Nav1.3, SCN5A/Nav1.5, SCN9A/Nav1.7, SCN10A/Nav1.8, KCNA3/Kv1.3, KCNH2, EAAT1, KCNQ2/Kv7.2, KCNQ3/Kv7.3 or CLC5. Promotes ubiquitination and degradation of SGK1 and TNK2. Ubiquitinates BRAT1 and this ubiquitination is enhanced in the presence of NDFIP1. Plays a role in dendrite formation by melanocytes. Involved in the regulation of TOR signaling. Ubiquitinates and regulates protein levels of NTRK1 once this one is activated by NGF. Plays a role in antiviral innate immunity by catalyzing 'Lys-29'-linked cysteine ubiquitination of TRAF3, resulting in enhanced 'Lys-48' and 'Lys-63'-linked ubiquitination of TRAF3. Ubiquitinates TTYH2 and TTYH3 and regulates protein levels of TTYH2.
Synonyms: KIAA0439; RSP5; NEDD4-2; NEDD4.2; PVNH7; hNEDD4-2
Tractability: Small molecule: a structure with a bound ligand is known; it has a binding pocket of medium quality. Antibody: its Gene Ontology location is reachable by antibodies, with high confidence. PROTAC: UniProt records ubiquitination sites on it; ubiquitination databases record sites on it; its protein half-life has been measured.
Gene: Protein-coding gene on chromosome 18 (58,044,050 to 58,401,540, forward strand). Ensembl gene ENSG00000049759.
Subcellular location: Cytoplasm; Golgi apparatus; Endosome, multivesicular body
Pathways (Reactome):
Signal Transduction: Downregulation of SMAD2/3:SMAD4 transcriptional activity; Downregulation of TGF-beta receptor signaling
Disease: Budding and maturation of HIV virion
Immune System: Antigen processing: Ubiquitination & Proteasome degradation
Transport of small molecules: Stimuli-sensing channels
Gene Ontology:
Molecular function: potassium channel inhibitor activity; protein binding; sodium channel inhibitor activity; sodium channel regulator activity; transmembrane transporter binding; ubiquitin protein ligase activity; ubiquitin-protein transferase activity
Biological process: negative regulation of potassium ion export across plasma membrane; negative regulation of potassium ion transmembrane transport; negative regulation of protein localization to cell surface; negative regulation of sodium ion import across plasma membrane; negative regulation of sodium ion transmembrane transport; positive regulation of dendrite extension; proteasome-mediated ubiquitin-dependent protein catabolic process; protein K48-linked ubiquitination; protein ubiquitination; regulation of membrane depolarization; regulation of membrane potential; regulation of membrane repolarization; regulation of protein stability; regulation of sodium ion transmembrane transport; ubiquitin-dependent protein catabolic process; monoatomic ion transmembrane transport; neuromuscular junction development; neuron projection development; positive regulation of caveolin-mediated endocytosis; receptor catabolic process; receptor internalization; regulation of dendrite morphogenesis; regulation of synapse organization; ventricular cardiac muscle cell action potential; negative regulation of sodium ion transport; and 2 more
Cellular component: apical plasma membrane; cytoplasm; extracellular exosome; Golgi apparatus; plasma membrane; cytosol; nucleoplasm; multivesicular body
Genetic constraint (gnomAD): Loss-of-function variants: 24 observed, 73.89 expected, observed/expected ratio (o/e) 0.32, 90% interval 0.23 to 0.46. The upper end of that interval is the gene's LOEUF score, 0.46, which puts it in group 2 of 6, group 1 being the genes least tolerant of losing a copy. Missense variants: 589 observed, 828.09 expected, observed/expected ratio (o/e) 0.71, 90% interval 0.66 to 0.76. Synonymous variants: 287 observed, 310 expected, observed/expected ratio (o/e) 0.93, 90% interval 0.84 to 1.02.
Gene-disease validity (ClinGen):
ClinGen rates the evidence that NEDD4L causes each of these diseases.
periventricular nodular heterotopia 7 (autosomal dominant): Definitive.
Homologues: Orthologues: guinea pig NEDD4L (98% identical), dog NEDD4L (98% identical), mouse Nedd4l (97% identical), chimpanzee NEDD4L (93% identical), pig NEDD4L (91% identical), rabbit NEDD4L (90% identical), macaque NEDD4L (90% identical), rat Nedd4l (89% identical), tropical clawed frog nedd4l (81% identical), zebrafish nedd4l (74% identical). Paralogues in human: NEDD4 (57% identical), HUWE1 (32% identical), WWP1 (32% identical), ITCH (32% identical), WWP2 (31% identical), HECW1 (31% identical), HECW2 (30% identical), SMURF2 (29% identical), UBR5 (27% identical), SMURF1 (27% identical), HACE1 (23% identical), HECTD4 (19% identical), and 12 more.
Diseases named in the same sentence as NEDD4L in open-access papers:
NEDD4L is named in the same sentence as 209 diseases in open-access papers, as found by Europe PMC text mining. Sharing a sentence is not in itself a finding about the gene and the disease. The quoted sentences say what the papers report.
Hypertension (37 papers, 2007 to 2025). The presence of chronic increased pressure in the systemic arterial system. "In this broader context, NEDD4L has been implicated in heritable hypertensive-disease Liddle Syndrome, hypertension, and cardiac dysfunction." (PMID 38309503, 2024). "A series of clinical and basic research have demonstrated that NEDD4L is associated with hypertension." (PMID 38526036, 2024). "A clinical study showed that Nedd4L gene single nucleic acid polymorphisms (SNPs) were closely related to hypertension." (PMID 35429991, 2022). "Genetic variation of Nedd4L (human Nedd4-2) is associated with developmental disorders, hypertension, and end-stage renal disease." (PMID 33854040, 2021). "Recently, studies showed evidence for the association of NEDD4L with obesity, a key intermediate phenotype in hypertension." (PMID 23549273, 2013). "Rs4149601 (16229 bps from exon 2) of NEDD4L is associated with hypertension in African Americans and Caucasians and rs3865418 (4106 bps from exon 13) has been shown to have a "flip-flop" association with hypertension in two Caucasian samples." (PMID 20003179, 2009). "In summary, two common SNPs of NEDD4L (296921-296923delTTG and rs2288775), were found to be associated with essential hypertension in Kazakh females." (PMID 20003179, 2009). "It appears that two common SNPs (296921-296923delTTG and rs2288775) in the NEDD4L and/or neighboring genes are associated with essential hypertension in females." (PMID 20003179, 2009). "NEDD4L is also associated with hypertension and miR-30a-attenuated atherosclerosis." (PMID 40136477, 2025). "Many studies have shown that the NEDD4L gene polymorphisms may influence hypertension by inhibiting the epithelial sodium channel (ENaC—amiloride-sensitive epithelial Na+ channel) through ubiquitination during increased salt intake." (PMID 39859138, 2025). "In humans, NEDD4L is involved in the process of several diseases, including the inhibition of hepatocellular carcinoma cell growth and involvement in viral replication, while its mutation is associated with hypertension in chronic kidney disease." (PMID 36421827, 2022). "Although these informative studies shed light on the associations of NEDD4L and hypertension and smoking independently, our study expands this work by examining and the independent and interactive effects of genetics and smoking on blood pressure among an African American population." (PMID 26752167, 2016). "However, a marked haplotypic diversity has previously been observed within NEDD4L such that opposite alleles of the same SNPs associate with hypertension in different white populations." (PMID 21060895, 2010). "Importantly, by studying some functional SNPs of NEDD4L chosen from the public genetic database, several studies have recently demonstrated that genetic variations of NEDD4L are associated with hypertension." (PMID 20003179, 2009). "Impaired interaction between ENaC and NEDD4L due to mutated PY motifs reduces NEDD4L-mediated ENaC ubiquitination, thereby decreasing ENaC endocytosis from the plasma membrane, leading to abnormally high sodium retention and ultimately hypertension." (PMID 19364400, 2009). "In this study, we systemically studied the association of genetic variations of NEDD4L with essential hypertension in Xinjiang Kazakh using the research strategy that we first screened genetic variations of NEDD4L and then studies the relationship of the representative SNPs to hypertension." (PMID 20003179, 2009). "In this study, one haplotype of NEDD4L was significantly associated with essential hypertension." (PMID 20003179, 2009). "The genetic variations of NEDD4L may be associated with essential hypertension in females in the Kazakh general population." (PMID 20003179, 2009). "Additionally, the NEDD4L gene is associated with hypertension and epithelial sodium transport." (PMID 41220585, 2025). "It is shown that the Nedd4L gene may be a candidate gene that causes high blood pressure in humans." (PMID 35429991, 2022).
Hypertension (continued). "Keywords such as “NEDD4L”, “atherosclerosis”, “signaling pathway”, “cardiovascular health”, “inflammation”, “diabetes”, “hypertension”, “endothelial dysfunction”, “endothelial cells”, and “lipids” were used." (PMID 40136477, 2025). "Haplotype analysis of the candidate genes KCNJ1, NEDD4L, BDKRB2, and CACNA1C was performed to investigate the potential associations with hypertension." (PMID 39859138, 2025). "Given that preeclampsia is a pregnancy-specific hypertensive disorder, the involvement of NEDD4L in hypertension suggests a potential link between NEDD4 and preeclampsia." (PMID 41220585, 2025). "In particular, NEDD4L regulates cellular growth and proliferation and acts during cardiovascular diseases and outcomes, including hypertension, cardiac remodeling, and atherosclerosis." (PMID 40136477, 2025). "Previous studies have proved that NEDD4L plays an important role in hypertension and atherosclerosis." (PMID 38526036, 2024). "The E3 ubiquitin ligase NEDD4L is involved in a wide range of regulatory physiology and pathology conditions, such as hypertension, cardiovascular disease and tumorigenesis." (PMID 38526036, 2024). "Accumulating evidence shows that NEDD4L is involved in the formation and development of hypertension at the molecular level by regulating sodium homeostasis and also participates in various cardiovascular diseases." (PMID 38526036, 2024). "The human Nedd4L gene, especially the evolutionary new subtype I, is a candidate gene for hypertension." (PMID 35429991, 2022). "Accumulating evidence show that, Nedd4L is involved in the formation and development of hypertension at the molecular level." (PMID 35429991, 2022). "Three representative Nedd4L variants (296921-296923delTTG, rs2288774, and rs2288775) were found to be related to EH in the general Kazakh population in a case survey study among Kazakh women, suggesting that the Nedd4L gene variant may be associated with the essential hypertension in Kazakh’s women." (PMID 35429991, 2022). "The IL17A-SGK1/NEDD4L-dependent pathway modulates renal sodium transport by improving renal function in hypertension and other autoimmune disorders." (PMID 33110392, 2020). "Nedd4-2 (NEDD4L) variants and single nucleotide polymorphisms (SNPs) are known to be associated with human hypertension and end-stage renal disease due to autosomal dominant polycystic kidney disease and juvenile nephronopthisis." (PMID 31802037, 2020). "NEDD4L was originally identified as an E3 ubiquitin ligase that ubiquitylates and degrades epithelial sodium channels in the regulation of hypertension." (PMID 33282879, 2020). "A SNP within NEDD4L (rs4149601) has been separately associated to ADHD, hypertension and blood pressure, and another SNP (rs2288774) has also been associated with ADHD." (PMID 21060895, 2010). "So NEDD4L is an important candidate gene for hypertension, and there is a need to study its relationship to hypertension comprehensively from a genetic point of view." (PMID 20003179, 2009). "Next, we looked for an association in the Kazakh general population between selected representative SNPs of NEDD4L and essential hypertension." (PMID 20003179, 2009). "As a secondary analysis, we also hypothesized that genetic variation in ADRB1, CYP3A5, and NEDD4L genes may explain BP variation in hypertension." (PMID 39063918, 2024). "The following factor might be involved in the induction of hypertension in Nedd4L knockout mice: Upregulated expression levels of all three ENaC subunits in the kidneys." (PMID 35429991, 2022). "Certain small-molecule compounds could destabilize cell-surface ENaC or enhance the Nedd4L activity in the kidney, thus being hopeful candidates for anti-hypertension agents." (PMID 35429991, 2022). "It remains unknown if targeting Nedd4L could be the hopeful option for target organ protection of hypertension." (PMID 35429991, 2022).
Hypertension (continued). "Therefore, it is of importance to further define the role and mechanism of Nedd4L ubiquitination in the protection of target organs in hypertension." (PMID 35429991, 2022). "WNK1 activates SGK1, inhibits NEDD4L, enhances ENaC activity and leads to hypertension." (PMID 33110392, 2020). "However, there are no reports regarding the relationship between genetic variations in the human NEDD4L gene and essential hypertension in Kazakh, which is an ideal population to study genetic mechanisms of hypertension." (PMID 20003179, 2009). "NEDD4L is a candidate gene for hypertension, both functionally and genetically." (PMID 20003179, 2009). "We therefore hypothesized that not only common, but also rare genetic variations in NEDD4L, could contribute to hypertension." (PMID 20003179, 2009). "Interestingly, four of these genes (KCNMB1, NEDD4L, ADD1 and NPR3) have been implied in genetic susceptibility for hypertension, while two genes have been associated with genetic susceptibility for stroke (PDE4D) or myocardial infarction (ADD1)." (PMID 19750006, 2009). "The purpose of the current study was to investigate the relationship between the variation in NEDD4L and essential hypertension in Kazakh, which is a relatively isolated population with a pure genetic background and is an ideal population to study genetic mechanisms of hypertension." (PMID 20003179, 2009). "This reconfirms that genetic variations of NEDD4L might be involved in the pathogenesis of essential hypertension." (PMID 20003179, 2009). "Furthermore, NEDD4L plays a vital role in hypertension and arrhythmia." (PMID 33110392, 2020). "Subjects with salt sensitivity and hypertension due to Nedd4L abnormalities might be at higher risk for more serious cardiovascular involvement than those without Nedd4L abnormalities." (PMID 28613240, 2017). "Thus, NEDD4L is a candidate gene for essential hypertension." (PMID 20003179, 2009). "In addition, knockout of Nedd4L protein from adult mouse renal tubules can lead to the accumulation of ENaC, which may lead to increased cell surface channels and sodium reabsorption in distal nephrons, and ultimately resulting in hypertension." (PMID 35429991, 2022). "have found that Nedd4L is highly expressed in aldosterone-sensitive distal nephron (ASDN) near to the collecting duct, indicating its role on hypertension." (PMID 35429991, 2022). "A novel common SNP (296921-296923delTTG) in NEDD4L, which is not found in the NCBI SNP-database, was significantly associated with essential hypertension in Kazakh females." (PMID 20003179, 2009). "Ang II decreases ACE2 protein through NEDD4L-mediated ubiquitination, causing hypertension, while ACE2 regulation in female mice may not be linked to Nedd4-2." (PMID 41303587, 2025). "Patients with salt sensitivity and hypertension because of NEDD4L anomalies may be more prone to severe cardiovascular ailments compared with individuals without NEDD4L anomalies." (PMID 33110392, 2020).